RANBP1 (RAN binding protein 1)
Diseases named in the same sentence as RANBP1 in open-access papers:
RANBP1 is named in the same sentence as 40 diseases in open-access papers, as found by Europe PMC text mining. Sharing a sentence is not in itself a finding about the gene and the disease. The quoted sentences say what the papers report.
colorectal cancer (5 papers, 2006 to 2025). A primary or metastatic malignant neoplasm that affects the colon or rectum. "Emerging evidence has indicated that RANBP1 is associated with poor prognosis of breast cancer and has been shown to influence miRNA expression in colorectal cancer." (PMID 40839321, 2025). "Our previous research demonstrated that elevated RANBP1 expression independently predicted poor colorectal cancer prognosis, promoted tumor cell proliferation and invasion, and inhibited apoptosis." (PMID 41186818, 2025). "Our earlier research demonstrated that RANBP1 is involved in colorectal cancer progression; however, the precise functions and significance of RANBP1 in TNBC progression and metastatic events have not yet been fully explored." (PMID 41186818, 2025). "More recently, it was discovered that decreased RANBP1 significantly reduces the expression of hsa-miR-18a, hsa-miR-183, and hsa-miR-106 (miRNAs) in colorectal cancer by preventing the nuclear transfers of the corresponding pre-miRNAs." (PMID 36911728, 2023). "Evidence suggests that RANBP1 modulates pre-miRNA nuclear transportation to affect colorectal cancer cell proliferation, invasion, and apoptosis." (PMID 36911728, 2023). "RANBP1 inhibits the proliferation of colorectal tumors, which negatively correlated with the paclitaxel sensitivity of colorectal cancer cells." (PMID 35845138, 2022). "Among the up-regulated genes in colorectal cancer, we found 14 genes involved in signal transduction (TDGF1 and ENC1), transcription (SOX9, MYC, and HGFR/MET), nuclear transport (NUP62, NUPL1, NUP155, KPNA2, RANBP5, CSE1L/CAS, NTF2, and RANBP1) and cellular transport (SLCO4A1)." (PMID 16919171, 2006).
22q11.2 deletion syndrome (4 papers, 2016 to 2023). 22q11.2 deletion syndrome (DS) is a chromosomal anomaly which causes a congenital malformation disorder whose common features include cardiac defects, palatal anomalies, facial dysmorphism, developmental delay and immune deficiency. "Lastly, RANBP1 (RAN Binding Protein 1) is a protein-coding gene linked with Digeorge Syndrome." (PMID 37486921, 2023). "22q11 proximal deletion, also known as DiGeorge syndrome or velocardiofacial syndrome, involves more than 30 Mendelian genes; potential genes such as TBX1, COMT, UFD1L, GNB1L, TRXR2, MED15, and RANBP1 were researched to explore the phenotype/CNV correlation." (PMID 32863884, 2020).
breast carcinoma (4 papers, 2021 to 2025). "MCF7, a breast cancer cell line which expresses high levels of PlexinB1, were treated with Sema4D, and RanGTP levels were detected with RanBP1(RBD)-GST, which binds to GTP-bound Ran specifically." (PMID 37563360, 2023). "Rather clear, however, is the link between the overexpression of nuclear export components, such as RANBP1 and the poor prognosis of breast cancer." (PMID 36672435, 2023).
colon carcinoma (4 papers, 2020 to 2023). "The increased regulation of RanBP1 expression in resistant cell lines in response to PLX4032 challenge further supports the relevance of the mechanisms regulating initiation of centrosome duplication in the development of drug resistance in BRAF-mutated colon cancer cells." (PMID 34201061, 2021). "The same pattern of RanBP1 expression recorded in resistant cell lines after the treatment with vemurafenib lends further support to the idea that the development of resistance to vemurafenib in BRAF-mutated colon cancer cells is associated with centrosome amplification and mitotic progression." (PMID 34201061, 2021). "In the original evidence, it was demonstrated that SGK1, through a phosphorylation-dependent positive regulation of SP1, induces a potent and stable transcriptional activity of RANBP1 in colon carcinoma cell lines." (PMID 36672435, 2023). "Further insight into the topic of the RANBP1 role in colon cancer and microRNAs transport comes from evidence from the high expression of RANBP1 in CRC (colon-rectal carcinoma) tissues of patients." (PMID 36672435, 2023). "Since many of these proteins including NPM1, RanBP1, eIF4E and PSPH were previously reported to be transcriptional targets of c-Myc, expression of c-Myc in colon cancer cell lines differing in their BRAF mutational status was also examined." (PMID 34201061, 2021). "SGK1 also enhanced the transcript levels RAN-binding protein 1 (RANBP1), a major effector of the GTPase RAN, and decreased Taxol sensitivity in RKO colon carcinoma cells." (PMID 33542904, 2020). "Although not significant, mRNA expression levels of ENOPH1, RANBP1 and EIF4E were higher in BRAFV600E mutant colon cancer than in the unaltered group." (PMID 34201061, 2021).
microcephaly (4 papers, 2019 to 2024). A congenital or acquired developmental disorder in which the circumference of the head is smaller than normal for the person's age and sex. "Full Ranbp1 loss-of-function is lethal around birth and has a variety of developmental consequences including acting as an apparent microcephaly gene." (PMID 37231803, 2024). "Gross microcephaly is seen in late gestation Ranbp1−/− fetuses." (PMID 37231803, 2024). "Interesting in this respect is the implication in microcephaly, in addition to the OMIM-recognized genes, of the gene encoding RAN-binding protein 1 (RANBP1), a regulator of the RAN nucleotide guanosine triphosphate (GTP) hydrolase (GTPase), that controls centrosome cohesion." (PMID 31878213, 2019). "In addition, mice with a homozygous deletion of Ranbp1 also show microcephaly or exencephaly." (PMID 34073122, 2021).
glioma (3 papers, 2016 to 2024). A benign or malignant brain and spinal cord tumor that arises from glial cells (astrocytes, oligodendrocytes, ependymal cells). "In this study, we observed a high expression of Ran-binding protein 1 (RanBP1) in lung cancer stem cells (LCSCs) and glioma stem cells (GSCs)." (PMID 37047826, 2023). "RanBP1 localized exclusively to the cytoplasm in untreated glioma cells, but RanBP1 nuclear accumulation was observed as early as 2 h post-exposure to S109 in both U87 and U251 cells." (PMID 27733172, 2016). "To examine whether S109 reversibly binds to CRM1 in glioma cells, we analyzed the subcellular localization of RanBP1 after cell transfer from S109-containing medium to S109-free medium." (PMID 27733172, 2016). "In this study, IL-18 was found to be regulated by RanBP1 in lung cancer stem cell (LCSC) and glioma stem cell (GSC), and CSC characteristics and EMT were regulated through this signaling mechanism." (PMID 37047826, 2023). "The RanBP1 gene is overexpressed in ALDH1+ lung cancer cells and CD133+ glioma cells." (PMID 37047826, 2023). "To investigate whether S109 is capable of functionally inactivating CRM1 in glioma cells, we analyzed the subcellular localization of NES-GFP and RanBP1, which are canonical markers of CRM1 inhibition." (PMID 27733172, 2016).
ovarian carcinoma (3 papers, 2015 to 2023). A malignant neoplasm originating from the surface ovarian epithelium. "The network of small-GTPases RAN proteins, of which RANBP1 is one of the main effectors, has also been demonstrated involved in the onset and progression of epithelial ovarian cancer (EOC)." (PMID 36672435, 2023). "To further investigate the in vivo role of RanBP1 in CD147-modulated paclitaxel response, we performed a xenograft assay in immunodeficient mice with cells from the ovarian cancer cell line SK-OV-3 overexpressing CD147 and/or shRNAs targeting RanBP1 (shRanBP1)." (PMID 34974521, 2022). "To investigate whether S109 is able to functionally inactivate CRM1 in ovarian cancer cells, we analyzed the subcellular localization of CRM1 cargo protein RanBP1, which is a canonical biomarker for CRM1 inhibition." (PMID 26055813, 2015).
cleft palate (1 paper, 2023). Cleft palate is a fissure type embryopathy that affects the soft and hard palate to varying degrees. "While no Cre-driver is perfectly efficient, Wnt1-Cre and Krt14-Cre have been used in multiple conditional-knockout models of cleft palate, and both ablate Ranbp1 efficiently in their appropriate compartments." (PMID 36790128, 2023). "Overt cleft palate is present in a significant number of individuals with 22q11DS (~11%; 4); therefore, it is of significant interest that Ranbp1 null mutants have a partially penetrant cleft palate phenotype." (PMID 36790128, 2023).
fragile X syndrome (1 paper, 2017). A genetic syndrome caused by mutations in the FMR1 gene which is responsible for the expression of the fragile X mental retardation 1 protein. "First, we cite the involvement of RANBP1 in the metabotropic glutamate receptor (mGluR) gene network, which is disrupted in two other syndromic forms of ASD, fragile X syndrome and tuberous sclerosis complex." (PMID 29090080, 2017).
liver cirrhosis (1 paper, 2024). "The comparative analysis identified four platelet proteins, namely Ras-related protein Rab-7a (Rab-7a), Ran-specific binding protein 1 (RANBP1), Rho GDP-dissociation inhibitor 1 (RhoGDI1), and 14–3-3 gamma with progressively decreased protein expression in patients with liver cirrhosis." (PMID 38279183, 2024).
melanoma (1 paper, 2015). A malignant, usually aggressive tumor composed of atypical, neoplastic melanocytes. "Consistent with this, four key nuclear transport factors, including CRM1, RanGAP1, Ran and RanBP1, are overexpressed in metastatic melanomas compared to primary melanomas and melanocytic nevi." (PMID 26506250, 2015).
osteosarcoma (1 paper, 2015). A usually aggressive malignant bone-forming mesenchymal neoplasm, predominantly affecting adolescents and young adults. "The here presented study detected a down-regulation of RANBP1 in osteosarcomas and pulmonary metastases cell lines by means of 2-DE protein profiling and Western blotting." (PMID 26203049, 2015). "Likewise in agreement with 2-DE results, RANBP1 levels were increased in fetal osteoblasts compared to osteosarcomas (p = 0.0083) and pulmonary metastases (p = 0.0424)." (PMID 26203049, 2015). "Two proteins were increased (GLO1, CTSD) and the other two were decreased (RANBP1, STMN1) in osteosarcomas and metastases based on the 2-DE expression profile." (PMID 26203049, 2015).
sarcoma (1 paper, 2015). A usually aggressive malignant neoplasm of the soft tissue or bone. "In contrast to RANBP1, CTSD was increased on the protein level in the sarcoma and metastatic cell lines with its highest expression in the sarcoma cell lines." (PMID 26203049, 2015).
schizophrenia (1 paper, 2023). A major psychotic disorder characterized by abnormalities in the perception or expression of reality. "Furthermore, SEZ6L2, CDIPTOSP, ASPHD1, and RANBP1 are potential candidate genes for schizophrenia." (PMID 37486921, 2023).
Tetralogy of Fallot (1 paper, 2023). A congenital cardiac malformation comprising pulmonary stenosis, overriding aorta, ventricular septum defect, and right ventricular hypertrophy. "Thus, the most severe cardiac anomalies associated with 22q11DS (interrupted aortic arch and/or tetralogy of Fallot) are not likely a significant feature of Ranbp1−/− embryos." (PMID 36790128, 2023).
viral infections (1 paper, 2018). "Other members of the network also reappeared in the gene set enrichment analysis as members of pathways associated with viral infections (DDX58, IFIT1, IRF1, MX1, STAT1) or viral carcinogenesis and cell cycle (CCND1, CCND3, CCNE1, CDC20, E2F2, RANBP1)." (PMID 30042828, 2018).
cancer (11 papers, 2016 to 2025). A tumor composed of atypical neoplastic, often pleomorphic cells that invade other tissues. "The NPM deficiency mediated by RANBP1 over-activity also results in the formation of supernumerary centrosomes and multipolar spindles, both conditions associated with most human cancer cells." (PMID 36672435, 2023). "Thus, more cancer mutations showed enhanced binding to CRM1 than to RanBP1." (PMID 35006421, 2020). "IHC staining of 87 pairs of cancer tissues and paraneoplastic tissues showed RANBP1 to be significantly up-regulated in TNBC tissues." (PMID 41186818, 2025). "Recent studies have shown that RanBP1 controls spindle checkpoint formation and seems to be affected in some cancers." (PMID 37686380, 2023). "In particular, RanBP1 is known to be involved in cancer induction by regulating pre-miRNA nuclear export." (PMID 37047826, 2023). "In this study, it was confirmed that IL-18 is regulated by RanBP1, and that cancer stem cells (CSCs) and the epithelial−mesenchymal transition (EMT) phenomenon are regulated by IL-18." (PMID 37047826, 2023). "Over time, RANBP1 has been demonstrated to be variously involved in human cancers both for the role in controlling nuclear transport and RAN activity and for its ability to determine the efficiency of the mitotic process." (PMID 36672435, 2023). "Our previous work showed that the effectiveness of the spindle poison paclitaxel in inhibiting cancer cell growth was dependent on the expression of RANBP1, a regulatory target of the serine/threonine kinase SGK1." (PMID 29340013, 2017). "Several researchers have reported that RanBP1 is involved in cancer malignancy." (PMID 37047826, 2023). "We showed that LCSC and GSC are regulated by RanBP1, and we speculated that miRNAs regulated by RanBP1 may act in the regulation of cancer malignancy." (PMID 37047826, 2023). "This indicates that RanBP1 is an important therapeutic target in cancer." (PMID 37047826, 2023). "RanBP1 can modulate the cancer microenvironment by regulating the cytokine IL-18." (PMID 37047826, 2023). "They consider that Sgk1 overexpression may have a central role in cancer due to its ability to regulate the Ran/RanBP1 pathway." (PMID 26985906, 2016). "RanBP1 is a major effector of Ran and could potentially be a target for cancer therapy." (PMID 26985906, 2016). "The cytokine IL-18 was regulated by RanBP1, and IL18 regulated cancer stem cell and EMT characteristics." (PMID 37047826, 2023). "RANBP1, in turn, is regulated by the serum- and glucocorticoid-regulated kinase 1 (SGK1), a serine/threonine kinase that plays a key role in cancer signal transduction." (PMID 29340013, 2017). "In previous work, we showed that cancer cells displaying increased SGK1 activity, and hence increased RANBP1 levels, become less sensitive to the effects of the microtubule-stabilizing agent paclitaxel." (PMID 29340013, 2017). "To determine whether CD147 regulates paclitaxel response via RanBP1, we treated cancer cells stably overexpressing CD147 with paclitaxel and silenced RanBP1 by siRNAs." (PMID 34974521, 2022). "Since this phenomenon has been observed in cancer cell lines as well as in a noncancerous primary fibroblast cell line, SGK1 and RANBP1 may participate in the general physiologic control of miRNA transport and maturation, increasing the overall impact and biological value of the data." (PMID 28358001, 2017).
tumor (3 papers, 2020 to 2025). "HE and IHC staining demonstrated that decreased RANBP1 expression corresponded with reduced Ki-67, a proliferation marker in tumor cells." (PMID 41186818, 2025). "Mechanistically, RANBP1 enhances miR-769-5p levels, promoting tumor growth and invasion by downregulating PRUNE2." (PMID 41186818, 2025). "RANBP1 affects the tumor immune microenvironment and was found to be over-expressed in TNBC patient samples during the current work." (PMID 41186818, 2025). "RANBP1 protein levels were evaluated in 87 TNBC tumor and adjacent normal tissues by immunohistochemistry." (PMID 41186818, 2025). "Specifically, higher frequencies of tumor cells, ECs, B cells, and macrophages were observed in the group exhibiting elevated RANBP1 expression, while T cells predominated in the low expression cohort." (PMID 41186818, 2025). "In summary, RANBP1 critically modulates the tumor immune microenvironment in TNBC, and its overexpression strongly correlates with adverse clinical outcomes." (PMID 41186818, 2025). "Functional assays demonstrated that RANBP1 knockdown markedly inhibited tumor cell proliferation and migratory capacity." (PMID 41186818, 2025). "High RANBP1 expression correlated with increased tumor cells, B cells, macrophages, and epithelial cells, and reduced T cells." (PMID 41186818, 2025). "In this context, which frames the role of RANBP1 in neoplastic deregulation and the ability of RANBP1 to mediate chemo- and radio-resistance phenomena in several tumor cell lines, primary cell models and in vivo plays a diriment role." (PMID 36672435, 2023). "In recent years, translational clinical works based on the analysis of RANBP1 expression levels, and connections with in vivo tumor phenotypes and neoplastic advancement are largely growing." (PMID 36672435, 2023). "Importantly, tumor cells specifically showed notably increased RANBP1 expression in the high-expression subset (p < 0.0001)." (PMID 41186818, 2025). "RANBP1 was over-expressed in tumor samples from TCGA-BRCA database." (PMID 41186818, 2025). "This study identifies RANBP1 as an oncogenic factor in TNBC and investigates its role in modulating T cell infiltration and tumor progression." (PMID 41186818, 2025). "IHC analysis was performed on paired tumor and adjacent normal tissue specimens from 87 TNBC patients, stratified into low RANBP1 (n = 56) and high RANBP1 (n = 31) expression cohorts based on the differential expression threshold." (PMID 41186818, 2025). "Mechanistically, RANBP1 upregulates oncogenic miR-769-5p, which suppresses PRUNE2, a tumor suppressor that normally inhibits TNBC progression." (PMID 41186818, 2025).
infection (1 paper, 2022). The state of being infected such as from the introduction of a foreign agent such as serum, vaccine, antigenic substance or organism. "Interestingly, both RanA and RanBP1 are localized to the bacteria-containing vacuole upon infection with Legionella, further strengthening a possible physical interaction." (PMID 34565293, 2022).
RANBP1 also shares sentences with these, for which no sentence is quoted: hepatic carcinoma (2 papers); autism (1); autism spectrum disorder (1); bacterial infections (1); chronic kidney disease (1); colon (1); colorectal tumors (1); glioblastoma (1); immune system disease (1); lung carcinoma (1); Marfan syndrome (1); nasopharyngeal carcinoma (1); nephrotic syndrome (1); Neurodevelopmental delay (1); rectal carcinoma (1); scoliosis (1); serous ovarian carcinomas (1); squamous cell carcinoma (1); triple-negative breast carcinoma (1); tuberculosis (1); tuberous sclerosis complex (1).